LINC00645 (long independently transcribed non-coding RNA 645)
Gene: Long non-coding RNA gene on chromosome 14 (27,529,238 to 27,639,636, forward strand). Ensembl gene ENSG00000258548.
Diseases named in the same sentence as LINC00645 in open-access papers:
LINC00645 is named in the same sentence as 7 diseases in open-access papers, as found by Europe PMC text mining. Sharing a sentence is not in itself a finding about the gene and the disease. The quoted sentences say what the papers report.
endometrial cancer (3 papers, 2020 to 2023). Primary or metastatic malignant neoplasm involving the endometrium (mucous membrane that lines the endometrial cavity). "LINC00645 is significantly upregulated in malignant endometrial cancer compared to normal endometrium." (PMID 32793467, 2020). "In addition, we found that LINC00645 plays an oncogenic role in endometrial cancer and glioma with high specificity." (PMID 37968670, 2023).
breast tumor (1 paper, 2024). "The capability of STGIC is validated indirectly by expression of marker genes of invasive breast tumor in the predicted spatial domains, which are C6orf141, PDE5A, LINC00645, BMERB1, ABCC11, ABCC12." (PMID 38416785, 2024).
lung carcinoma (1 paper, 2020). "Result revealed a 6 lncRNA signal, including LINC01287, SNAP25-AS1, LINC00470, AC104809.2, LINC00645 and LINC01010, as an independent prognostic factor for predicting OS in lung cancer patients." (PMID 32518519, 2020).
tumor (3 papers, 2023). "Depletion of LINC00645 reduced tumour growth of the tumour xenograft model in vivo." (PMID 37891744, 2023). "Correlation analysis in the TCGA-KIRC dataset revealed that RP11-528A4.2 was negatively correlated with patient age, LINC00645 was negatively correlated with tumor stage, PTCSC3 was positively correlated with gender, and AP000696.2 was positively correlated with tumor stage, T stage, and M stage." (PMID 37968670, 2023).
LINC00645 also shares sentences with these, for which no sentence is quoted: glioma (3 papers); cancer (1); esophageal squamous cell carcinoma (1).